JAK2 (Janus kinase 2)
Diseases named in the same sentence as JAK2 in open-access papers (continued):
Sharing a sentence is not in itself a finding about the gene and the disease.
myeloproliferative neoplasm (continued). "In humans, most patients with polycythemia vera (PV), one-half of the cases of essential thrombocythemia (ET), and other myeloproliferative neoplasms (MPNs) cases possess an JAK2 p.V617F mutation (exon 12) leading to constitutive activity of the JAK2 gene-encoded tyrosine kinase." (PMID 37570280, 2023). "Polycythemia vera (PV) is a myeloproliferative neoplasm driven by activating mutations in JAK2 that result in unrestrained erythrocyte production, increasing patients’ hematocrit and hemoglobin concentrations, placing them at risk of life-threatening thrombotic events." (PMID 36928379, 2023). "However, tyrosine kinases, particularly Janus kinase 2 (JAK2), have been linked to myeloproliferative diseases other than chronic myeloid leukemia." (PMID 38069330, 2023). "Recently in myeloproliferative disorders and myeloid malignancies researches, researchers discover JAK2 in the nuclear region of hematopoietic cells, and JAK2 nuclear translocation has been linked to conditions associated with high cell turnover in hematopoietic cells." (PMID 37194022, 2023). "Lastly, LoGoFunc predicted a GOF variant in JAK2, p.Val617Phe, which has been hypothesized to confer a proliferative advantage in hematopoietic precursor cells and was associated with myeloproliferative disease in BioMe BioBank." (PMID 38037155, 2023). "Given the fact that KDM4C was dispensable for normal hematopoietic stem- and progenitor cells, targeting this enzyme may represent a strategy to selectively target JAK2-mutated cells in myeloproliferative neoplasms." (PMID 35654819, 2022). "Six out of seven biomarker associations for JAK2 were only identified by kernel-based tests, and the gain of function variant driving these associations (V617F or rs7737549334) was also associated with myeloproliferative neoplasms." (PMID 36088354, 2022). "In addition, JAK2 mutation (JAK2V617F) has been associated with the incidence of myeloproliferative neoplasms." (PMID 35631587, 2022). "Thus, the aim of this review is to describe the main genetic, hematological and immunological findings that are linked to JAK2 variant signaling in chronic myeloproliferative neoplasms." (PMID 35204792, 2022). "Similarly, WGS of ~1,000 clonal haematopoietic colonies from patients with myeloproliferative neoplasms demonstrated that the acquisition of JAK2‐V617F driver mutations often occurred early in life, including during the in utero period." (PMID 35438189, 2022). "Janus kinase 2 (JAK2) hyperactivation by JAK2V617F mutation leads to myeloproliferative neoplasms (MPNs) and targeting JAK2 could serve as a promising therapeutic strategy for MPNs." (PMID 35256594, 2022). "They noted that finding the Val617Phe (point mutation of Janus kinase 2) mutation may become a good identifier to distinguish myeloproliferative diseases from other similar ones." (PMID 35453637, 2022). "While JAK2VF-driven myeloproliferative disorders are associated with increased hematocrit, platelet and leukocyte counts, mutations in JAK2 exon 12 have been identified in patients with myeloproliferative disorders who have isolated erythrocytosis and increased atherothrombotic events." (PMID 35587375, 2022). "Polycythemia vera (PV) is a BCR-ABL–negative myeloproliferative neoplasm marked by acquisition of an activating mutation of JAK2, which leads to not only erythrocytosis but also frequently to leukocytosis and thrombocytosis, and is associated with a high symptom burden and increased thrombotic risk." (PMID 33817698, 2021). "Evidence of molecular complexity including intra-lineage clonal evolution was found in another study of myeloproliferative neoplasms: two unusual patients, each harboring two driver mutations (JAK2/CALR and JAK2/MPL), which represented, in both cases, independent clones." (PMID 33810569, 2021).
myeloproliferative neoplasm (continued). "Similarly, the development of the JAK1/JAK2 kinase inhibitor ruxolitinib was driven by the high prevalence of mutations in JAK2 in myeloproliferative neoplasms." (PMID 34167562, 2021). "The V617F mutation in JAK2 is strongly associated with myeloproliferative neoplasms (MPNs), including myelofibrosis, polycythemia vera and essential thrombocythemia, occurring in nearly 100% of patients with polycythemia vera and over 75% of patients with essential thrombocythemia." (PMID 34371735, 2021). "CRT trails JAK2 as the second most mutated gene in myeloproliferative neoplasms (MPNs)." (PMID 33591948, 2021). "Increased JAK2 activity was associated with angiotensin II type 1 receptor-mediated hypertension and other cardiovascular diseases, JAK2 is activated in various myeloproliferative disorders, and JAK2 is overexpressed in polycystic kidney disease." (PMID 34067609, 2021). "Loss of function mutations in JAK3 result in Severe Combined Immunodeficiency Disease (SCID), as do mutations in the common gamma chain receptor which recruits JAK39–11 while activating mutations in JAK2 are a frequent cause of myeloproliferative disorders such as myelofibrosis and polycythaemia." (PMID 33980892, 2021). "The hypothesis that lipid and energy metabolisms are impaired in MF is consistent with a recent report indicating that the JAK2 mutation alters lipid and glucose metabolism in animal models of myeloproliferative neoplasms." (PMID 33312951, 2020). "A few types of myeloproliferative neoplasms may be significant for Janus-associated kinase 2 mutation, JAK2 V617F, including polycythemia vera, essential thrombocythemia, and primary myelofibrosis." (PMID 32685224, 2020). "Myeloproliferative neoplasms are characterized by mutations in JAK2, MPL and CALR genes." (PMID 33317584, 2020). "Reportedly, there is a relationship between JAK2 mutations and myeloproliferative diseases." (PMID 33585010, 2020). "JAK2 mutation in myeloproliferative diseases increases the risk of CVT." (PMID 32846801, 2020). "In this regard, the V617F mutation in JAK2, leading to gain in function, is a recurring feature of myeloproliferative disorders, and patients harboring this mutation have been shown to have a longer duration of disease and are also at increased risk for fibrosis." (PMID 32486130, 2020). "Association of JAK2 mutations with CH was first reported in 2005 when these mutations were detected in a vast majority of individuals with polycythemia vera (PV), a myeloproliferative disorder characterized by overproduction of erythrocytes and thrombocytes." (PMID 33114351, 2020). "There is variability of phenotypes in JAK2 mutation-containing myeloproliferative neoplasms." (PMID 31065022, 2019). "Therefore, the objective of this review is to characterize the studies of BCR-ABL1-negative chronic myeloproliferative neoplasms and to compare the frequency of JAK2, MPL and CALR mutations in PV, ET and PMF." (PMID 31208359, 2019). "BCR-ABL-driven chronic myeloid leukaemia (CML) and Janus kinase 2 (JAK2) V617F-mutated myeloproliferative neoplasm (MPN) cell lines showed similar results, suggesting a role for NOX-derived ROS in myeloid neoplasms driven by oncogenic tyrosine kinases more broadly." (PMID 31795243, 2019). "This point mutation in JAK2 is strongly associated with myeloproliferative neoplasms." (PMID 30717771, 2019). "The occurrence in most patients affected by myeloproliferative neoplasms (MPNs) of driver mutations resulting in the constitutive activation of JAK2-dependent signaling identified the deregulated JAK-STAT signal transduction pathway as the major pathogenic mechanism of MPNs." (PMID 31788449, 2019). "Somatic gain-of-function mutations in JAK2 are associated with myeloproliferative diseases." (PMID 30717771, 2019).
myeloproliferative neoplasm (continued). "Polycythemia Vera (PV) is a myeloproliferative disorder characterized by overproduction of morphologically normal red blood cells (RBCs), granulocytes, and platelets, a phenotype that is caused by a mutation (V617F) in Janus kinase 2 (JAK2)." (PMID 31652037, 2019). "In nine patients with myeloproliferative disease, eight (89%) were JAK-2 V617 mutation positive." (PMID 29777267, 2018). "The participant with the JAK2 p.V617F variant previously had myeloproliferative disorder at age 44, and had their blood drawn for DNA extraction approximately 20 years later; at their death aged 85 years, had no reported diagnosis of recurrent haematological malignancy." (PMID 29641532, 2018). "Conversely, the putative JAK2-dependent phosphorylation sites present in wild-type CALR suggest that in myeloproliferative disorders JAK2 mutations may affect the function of this protein." (PMID 29218307, 2017). "CALR trails JAK2 as the second most mutated gene in myeloproliferative neoplasms (MPNs)." (PMID 26377485, 2016). "Moreover, mutation in the JAK2 gene was reported in about 80% of patients with a diagnosis of myeloproliferative neoplasms." (PMID 26413812, 2015). "Mutations in the JAK2 gene have served as disease markers for myeloproliferative neoplasms (MPNs)." (PMID 25624900, 2015). "Importantly, it was shown that myeloproliferative neoplasms can be initiated from a single hematopoietic stem cell expressing V617F mutated JAK2." (PMID 26413812, 2015). "Many myeloproliferative neoplasms (MPNs) harbor point mutations in JAK2 (Janus kinase 2) that result in signaling hyperactivation involving signal transduction and activator of transcription factors (STATs), but constitutive PI3K/mTOR activation has also been implicated in MPNs." (PMID 24904824, 2014). "Furthermore, in some leukemias and myeloproliferative neoplasms, constitutive JAK2 activation (V617F mutation) drives malignant transformation and this prompted a significant effort in targeting JAK2 inhibition as a potential therapeutic strategy." (PMID 24930769, 2014). "Furthermore, autophosphorylation of JAK2V617F, a constitutive active Jak2 variant found in myeloproliferative diseases, was inhibited after CK2 suppression." (PMID 24742922, 2014). "Myeloproliferative disorders are associated with a somatic mutation in the JAK2 kinase." (PMID 25107306, 2014). "However, activating mutations of JAKs are found in association with malignant transformations, the most common being the gain-of-function V617F mutation of JAK2 in polycythemia vera and other myeloproliferative disorders." (PMID 25149535, 2014). "An activated mutant of Jak2, Jak2-V617F, is found in more than 90% of polycythemia vera and about 50% of essential thrombocythemia or primary myelofibrosis and is implicated in pathogenesis and progression of these myeloproliferative neoplasms." (PMID 24260231, 2013). "In 2005, several groups independently reported the discovery of a somatic mutation of the gene encoding JAK2 in a high proportion of patients with myeloproliferative neoplasms (MPNs) : >95% for polycythemia vera (PV), and 50% for essential thrombocythemia (ET) and primary myelofibrosis (PMF)." (PMID 23739681, 2013). "JAK2 V617F mutation is the most important biomarker in myeloproliferative neoplasms (MPN)." (PMID 24252729, 2013). "Since JAK2 kinase has been shown essential to the proliferation of hematopoietic stem cells, JAK2 mutations may be critical in the pathogenesis of myeloproliferative disease." (PMID 23853604, 2013). "Indeed, JAK2 V617F mutation frequently accompanied to chronic myeloproliferative disorders as polycythemia vera (PV) and essential thrombophilia (ET) in recent reports." (PMID 23876158, 2013). "This case illustrates the importance of testing for JAK2 V617F in patients presenting with Budd-Chiari syndrome, even in the absence of overt hematologic abnormalities, in order to establish a diagnosis of underlying myeloproliferative neoplasm." (PMID 22480324, 2012).
myeloproliferative neoplasm (continued). "Importantly, JAK2 activating mutations are critical in the pathogenesis of myeloproliferative disorders and that has led to the development of JAKs small molecule inhibitors." (PMID 23056499, 2012). "A high percentage of patients with the myeloproliferative disorder polycythemia vera (PV) harbor a Val617→Phe activating mutation in the Janus kinase 2 (JAK2) gene, and both cell culture and mouse models have established a functional role for this mutation in the development of this disease." (PMID 22623993, 2012). "The somatic valine-to-phenylalanine mutation in the pseudokinase domain of Jak2 (Jak2-V617F) has been found in the majority of patients with polycythemia vera and in about 50% of patients with the other myeloproliferative neoplasms, essential thrombocythemia and primary myelofibrosis." (PMID 22087308, 2011). "Most BCR-ABL1-negative myeloproliferative neoplasms (MPN) carry an activating JAK2 mutation." (PMID 21646683, 2011). "We previously found that gender influenced the JAK2 V617F allele burden, but it is unknown whether this gender difference in molecular epidemiology influences complications in the myeloproliferative neoplasms (MPNs)." (PMID 22084670, 2011). "For some oncogenic gain-of-function mutations, such as the V617F mutation in the tyrosine kinase JAK2 in myeloproliferative disorders, loss of the wild type allele could actually give an advantage to the tumor cell." (PMID 21899760, 2011). "The identification of an activating mutation in JAK2 as a cause of chronic myeloproliferative disease could have important clinical implications." (PMID 17032464, 2006). "This JAK2‐sparing profile may reduce the risk of cytopenias in PV patients requiring RA therapy, offering a potentially safer immunomodulatory option in individuals with underlying myeloproliferative disease." (PMID 41487987, 2026). "Thus, MRD evaluation could also be considered and linked to clinical evolution in pediatric cases of JAK2-mutated myeloproliferative neoplasms." (PMID 39903357, 2025). "The co‐occurrence of PRCA and myeloproliferative neoplasm (MPN) with JAK2 and MPL mutations is exceptionally rare." (PMID 41439212, 2025). "Myelodysplastic/Myeloproliferative Neoplasm with Ring Sideroblasts and Thrombocytosis (MDS/MPN-RS-T) can also share clinical (leukocytosis and thrombocytosis) and pathological (JAK2 mutation, hyperlobated megakaryocytes, fibrosis) with PMF." (PMID 41514563, 2025). "Alternatively, constitutive JAK/STAT signaling can be induced by the acquisition of gain-of-function mutations (e.g., JAK2 V617F) in hematopoietic stem cells leading to myeloproliferative neoplasm (MPN)." (PMID 40430208, 2025). "The JAK2-V617F mutation is the most frequent driver mutation in a group of malignant hematopoietic disorders called myeloproliferative neoplasms (MPN)." (PMID 40790213, 2025). "This haplotype, which accounts for approximately 28% of the population-attributable risk of developing a myeloproliferative neoplasm (MPN), precedes the acquisition of the JAK2 V617F variant." (PMID 41226376, 2025). "The JAK2-V617F mutation is the most common genetic alteration in myeloproliferative neoplasms (MPN), which can progress to secondary acute myeloid leukemia (sAML), a chemotherapy-resistant disease with limited treatment options and a poor prognosis." (PMID 41332324, 2025). "Conceptually, this was first commonly recognized in familial clusters of myeloproliferative neoplasms (MPN) patients with somatic JAK2-V617F variants." (PMID 41457124, 2025). "Testing for the most common chronic myeloproliferative neoplasm-associated mutations, such as Janus kinase 2 (JAK2), Calreticulin (CALR), Myeloproliferative leukemia virus oncogene (MPL) genes, and performing a bone marrow biopsy may also aid in the diagnostic process." (PMID 40130200, 2025).
myeloproliferative neoplasm (continued). "Polycythaemia vera (PV) is a Janus kinase 2 (JAK2)–mutated myeloproliferative neoplasm (MPN) characterised by clonal erythrocytosis, with increased risk of thrombosis and progression to myelofibrosis or acute myeloid leukaemia." (PMID 40202537, 2025). "Primary myelofibrosis (PMF), a chronic myeloproliferative neoplasm (MPN) characterized by splenomegaly resulting from extramedullary hematopoiesis, is associated with the JAK2 V617F mutation." (PMID 41179685, 2025). "PBX1 may contribute to other hematopoietic cancers also in the absence of genomic alterations, for example, if overexpressed or if expressed in HSCs or MEPs in the presence of other driver mutations, such as the somatic V617F mutation in the JAK2 gene typical of myeloproliferative neoplasm (MPN)." (PMID 38404687, 2024). "In 2005, a somatic mutation in the JAK2 gene was identified in patients with myeloproliferative neoplasms (MPN)." (PMID 39682300, 2024). "We previously found that DDX5 played an essential role in the signaling pathway of the tyrosine kinase Janus kinase 2 (JAK2) V617F mutant, which causes myeloproliferative neoplasms (MPN)." (PMID 38612503, 2024). "Patients who have persistent thrombocytosis or other features suggestive of a myeloproliferative neoplasm (MPN) whilst in remission for CML should be tested for JAK2 V617F and other MPN driver mutations." (PMID 37794101, 2023). "The classical BCR::ABL1-negative myeloproliferative neoplasms such as polycythemia vera (PV), essential thrombocythemia (ET), and myelofibrosis (MF) are clonal diseases with the presence of characteristic “driver mutations” in one of the genes: JAK2, CALR, or MPL." (PMID 37745842, 2023). "Somatic activating mutations in JAK2 V617F located at 9p24 are very common in myeloproliferative neoplasms (MPN) and have been associated with an increased incidence of thrombosis, hemorrhage, and fibrosis." (PMID 36810551, 2023). "Polycythaemia vera (PV) is a chronic myeloproliferative neoplasm (MPN) characterised by a somatic activating mutation in the JAK2 gene that drives abnormal erythrocytosis, resulting in an abnormal increase in red blood cell mass." (PMID 37754671, 2023). "Polycythemia vera (PV) is a myeloproliferative neoplasm (MPN) that is caused by somatic gain-of-function mutations in the jak2 gene in hematopoietic stem and progenitor cells, most of which result in the JAK2V617F oncoprotein." (PMID 36564535, 2023). "The discovery of the activating V617F mutation in Janus kinase 2 (JAK2) has been decisive for the understanding of myeloproliferative neoplasms (MPN)." (PMID 35215273, 2022). "PRMT5 inhibition has also been studied in myeloproliferative neoplasms (MPN), especially in JAK2-mutated MPN with a decreased proliferation both in vitro and in patient samples." (PMID 36358861, 2022). "Polycythemia vera (PV) is a myeloproliferative neoplasm (MPN) characterized by uncontrolled clonal proliferation of multipotent bone marrow progenitors, sustained by acquired genetic mutations in JAK2 genes (JAK2 V617F and exon-12 mutations)." (PMID 35145055, 2022). "In addition to the JAK2 V617F variant pairs, immune thrombocytopenia, essential thrombocythemia, and chronic myeloproliferative disease were connected by SELENON G315S, which is indicated as pathogenic by ClinVar and has been associated with congenital myopathies among other diseases." (PMID 35945607, 2022). "Myelofibrosis is a myeloproliferative neoplasm (MPN) caused primarily by mutations that activate JAK2 signaling, resulting in splenomegaly and a marked expansion of hematopoietic cells in bone marrow." (PMID 35977945, 2022). "Interestingly, misregulation and mutation of JAK2 were observed frequently in many myeloproliferative diseases and various cancers, which suggested that JAK2 could be an important target for cancer treatment." (PMID 35207737, 2022).